ATR (ATR checkpoint kinase)
Diseases named in the same sentence as ATR in open-access papers (continued):
Sharing a sentence is not in itself a finding about the gene and the disease.
glioma (28 papers, 2018 to 2026). A benign or malignant brain and spinal cord tumor that arises from glial cells (astrocytes, oligodendrocytes, ependymal cells). "To evaluate the prognostic risk related to the enhancer-controlled genes associated with ATR pathway activation, we calculated the hazard ratio and 95% confidence interval (CI) of the overall survival of glioma patients using Cox proportional hazard models." (PMID 37349788, 2023). "RECQL4 knockdown in glioma and MPNST cell lines resulted in increased apoptosis and susceptibility to ATR-inhibitors." (PMID 41317405, 2025). "Here, we investigated Ataxia telangiectasia and Rad3 related (ATR) inhibition (ATRi) and functionally-instructed combination therapies involving ATRi in experimental glioma." (PMID 38475864, 2024). "Experimental glioma overexpressing basic helix loop helix (bHLH) transcription factors display a sensitization towards ATR inhibition (ATRi)." (PMID 38475864, 2024). "This study attempts to provide a theoretical foundation for the discovery of effective ATR pathway inhibition targets for glioma." (PMID 37349788, 2023). "ATR pathway plays important roles in the regulation of various processes such as apoptosis, DNA damage repair and drug resistance in glioma." (PMID 37349788, 2023). "Further elucidation of more detailed ATR pathway-related regulatory mechanisms in glioma needs to be explored." (PMID 37349788, 2023). "Consistent with previous findings in established cell lines, exposure of primary glioma stem-like cells (GSCs) to therapeutically relevant frequency of TTFields (200 kHz) caused DNA damage and activated both PARP1 and ATR signalling pathways." (PMID 37777579, 2023). "Given the key role of the ATR-mediated signalling pathway in cellular response to DNA damage and replication stress, the ATR kinase is an established oncology drug target in a range of tumours, including gliomas." (PMID 37777579, 2023). "Glioma biomarkers of predictive value for PARPi therapeutic efficacy include IDH1/2 mutations, a low BRCA1 expression, aberrant ATM or ATR signaling, MYC overexpression, and inactivation of mismatch repair genes, especially MSH6." (PMID 35406593, 2022). "In contrast to the glioma cell line SF188, combined ATRX knockout (KO) and TERC KO led to ALT-like properties and sensitized U251 glioma cells to ATR inhibition in vitro and in vivo." (PMID 35740680, 2022). "These O6MeG-dependent replication blocking lesions activate the DNA damage response (DDR) kinases ATM and ATR, thereby initiating bypass in glioma cells in a tolerance mechanism that requires homologous recombination (HR)." (PMID 35365623, 2022). "Based on our data, we conclude that ATR inhibition will be a promising candidate particularly in glioma with high bHLH expression and in combination with treatments inducing double strands breaks." (PMID 33134924, 2020). "Silencing ACTL6A can induce glioma cell apoptosis by inhibiting the ATR/CHK1 pathway." (PMID 37349788, 2023). "NUSAP1 enhances ATR stability by promoting its sumoylation and inhibiting its ubiquitin-dependent degradation, thereby promoting resistance to temozolomide and doxorubicin in glioma." (PMID 37349788, 2023). "Finally, besides employing small molecule ATMi, silencing of ATM or ATR using siRNA has also been shown to increase glioma cell chemo- and radiosensitivity." (PMID 35406593, 2022). "Finally, we investigated the effect of ATR inhibition and temozolomide treatment on orthotopic glioma xenografts in vivo." (PMID 35740680, 2022). "Treatment with ATM- or ATR-inhibitors (ATMi/ATRi) may thus selectively sensitize glioma cells and GSCs to IR and/or TMZ." (PMID 35406593, 2022).
glioma (continued). "Previous studies suggest DNA-PKcs and ATR expression are positively correlated in glioma models, which might suggest that the balance of the two pathways is important for cell viability." (PMID 36077823, 2022). "ATM and ATR were reported play vital roles in treatment-resistance in gliomas." (PMID 34483751, 2021). "Functional studies were performed in glioma (U251) and malignant peripheral nerve sheath tumors (MPNSTs) (NF90-8, ST88-14) cell lines following RECQL4 knockdown and treatment with ATR-inhibitors." (PMID 41317405, 2025). "ATR inhibition (ATRi) by AZD6378 and Berzosertib led to significant anti-glioma activity in human and murine glioma cell lines in vitro." (PMID 38475864, 2024). "Based on an analysis of U87vIII TMZ-treated bulk RNA-seq data we found that DNA replication, the E2F pathway, and ATR-related pathways were enriched in upregulated genes, supporting the important role of DDR in TMZ resistance among MGMTlow glioma cells." (PMID 37283490, 2023). "This cell line demonstrates sensitivity to ATR inhibition (AZD6738) in vitro while being resistant to temozolomide, a standard drug used in the treatment of high-grade glioma." (PMID 35740680, 2022). "DNA double-strand breaks (DSBs) and blocked DNA replication forks activate the DDR kinases ATM, ATR, CHK1 and CHK2 and these kinases protect glioma cells against TMZ-induced cell death." (PMID 35365623, 2022). "Glioma cells, especially GSCs, exhibit increased resistance to IR, which is mediated by an upregulation of DDR targets such as ATM, ATR, PARP1, and CHK1." (PMID 35406593, 2022). "Targeting replication stress response with combined ATR (ataxia telangiectasia and Rad3 related) and PARP (poly (ADP-ribose) polymerase) inhibition provides high and specific cytotoxicity in glioma cells." (PMID 35562993, 2022). "The ATM inhibitor (ATMi; KU-60019) and ATR inhibitor (ATRi; AZD6738) potently inhibit their target and effectively sensitised glioma cells (ATMi) and NSCLC cells (ATRi) to radiation and were used at doses with confirmed target inhibition." (PMID 33824328, 2021). "Particularly, artesunate, an artemisinin's derivative, provoked a DDR with phosphorylation of ATM, ATR, CHK1, and CHK2 in LN-229 glioma cells after 8-hour treatment, while timosaponin AIII activated DDR through the ATM-CHK2 pathway in MCF-7 cells after treatment for 10–20 min." (PMID 35287310, 2022). "EXT1-high tumors may be vulnerable to synthetic lethality approaches involving checkpoint inhibition (CHK1 or ATR inhibitors), whereas EXT2-driven gliomas might respond to combinatorial regimens targeting cytoskeletal remodeling or focal adhesion dynamics 73-75." (PMID 41438585, 2026). "In glioma cells, NEK1 drives proliferation and survival through a multifaceted DDR network in which TLK1 phosphorylates NEK1 on T141, fostering its interaction with the ATR–ATRIP complex and priming ATR autophosphorylation at T1989 for efficient CHK1 activation." (PMID 41154634, 2025). "The glioma cell line U251, which develops ALT after ATRX KO, was more sensitive to two different ATR inhibitors (AZD6738 and VE-822) in the absence of ATRX, in contrast to the SF188 cell line, which remains ALT-negative." (PMID 35740680, 2022).
lymphoma (25 papers, 2006 to 2025). A malignant (clonal) proliferation of B- lymphocytes or T- lymphocytes which involves the lymph nodes, bone marrow and/or extranodal sites. "The difference in the (phospho)proteome response to inhibitor treatment implied that the RelA T505A mutation was inducing a change or defect in ATR/CHK1 signalling in response to DNA replication stress in Eμ-Myc lymphoma cells." (PMID 36240065, 2022). "Subsequent examination of ATR/CHK1 signalling components revealed loss of expression of the ATR/CHK1 adaptor protein Claspin in RelA T505A Eμ-Myc lymphomas." (PMID 36240065, 2022). "More recently, two other splicing alterations of ATR have been reported in clinical samples with pyothorax-associated lymphoma." (PMID 17010193, 2006). "We also analysed the phosphoproteomic dataset from Eμ-Myc Rel−/− lymphomas for evidence of any general changes in ATR, Ataxia Telangiectasia Mutated (ATM) or DNA-Dependent Protein Kinase (DNA-PK, PRKDC) dependent phosphorylation, whose target phosphosites generally contain an SQ or TQ motif." (PMID 36240066, 2022). "Nilsson Lab first demonstrated that dual inhibition of BET proteins and ATR in MYC-induced lymphoma cells triggers pronounced DNA damage, apoptosis, and senescence, both in vitro and in vivo." (PMID 41561634, 2025). "The ATR inhibitor BAY 1895344 (Bayer) showed efficacy activity against certain lymphoma cell lines and in MCL xenograft models." (PMID 38347838, 2024). "Given their high level of replication stress, ATR inhibition is more likely to be successful in aggressive lymphomas with a high proliferative index, and these should be prioritized for future clinical trials." (PMID 38347838, 2024). "Consistent with heightened MYC activity, genes involved in the ATR response to replication stress were upregulated in lymphoma‐infiltrated spleens and in purified tumor cells relative to controls." (PMID 35510955, 2022). "In genetically engineered mouse models, reduction of ATR prevented MYC-driven lymphomas or pancreatic tumors." (PMID 25495526, 2014). "ATR inhibition may reverse the immune-silent state and enhance T cell–based immunotherapy in aggressive lymphomas with GC DZ–like characteristics." (PMID 40674145, 2025). "To evaluate the anti-lymphoma efficacy of the combination treatment in vivo, we choose a CDX model derived from ATM-deficient Granta-519 and treated the mice with inhibitors of PRMT5, and ATR, alone or together." (PMID 36797243, 2023). "Indeed, in lymphomas, cytosolic DNA presence is dependent on the downstream signaling of Ataxia Telangiectasia and Rad3-related protein (ATR) and to a lesser extent on ATM." (PMID 35198459, 2022). "We hypothesised therefore, that ATR/CHK1 signalling might be compromised in Eμ-Myc/cRel−/− lymphoma cells." (PMID 36240066, 2022). "We hypothesised that altered activation of CHK1 by ATR in response to MYC-induced DNA replication stress in Eμ-Myc/cRel−/− lymphoma cells could affect CHK1 inhibitor sensitivity." (PMID 36240066, 2022). "Since c-Rel has been described as an indirect regulator of CHK1 activity by inducing CLSPN gene expression, we were curious as to whether deleting c-Rel would affect ATR/CHK1 signalling in Eμ-Myc lymphomas and consequently the response to CHK1 inhibition." (PMID 36240066, 2022). "This experiment, originally performed before our RNA Seq and proteomic analysis of reimplanted Eμ-Myc lymphomas was completed, revealed lower levels of Claspin mRNA and protein expression in primary RelA T505A Eμ-Myc lymphomas, while ATR, CHK1, ATRIP, RAD17 and TOPBP1 were unaffected." (PMID 36240065, 2022). "In support of this concept, ATR/CHK1 pathway inhibition in combination with oncogene expression of H-rasG12V cells elevate H2AX phosphorylation to significantly higher levels than produced in control cells, and also ATR/CHK1 inhibitors are highly effective in killing Myc-driven lymphomas." (PMID 27167194, 2016).
lymphoma (continued). "On these bases, we functionally investigated whether ATR inhibition (ATRi) in lymphoma cells with a DZ-like transcriptional profile, could perturb the immunologically-cold status activating the expression of genes associated with inflammatory signaling, such as IFN-stimulated genes." (PMID 38562878, 2024). "To investigate the role of ATR in maintaining the DZ transcriptional program, we treated two DZ-like lymphoma cell lines, HT and SUDHL-5, with the ATR inhibitor (ATRi) ceralasertib (AZD6738) or DMSO control for 48 hours." (PMID 40674145, 2025). "In conclusion, through the characterization of a novel transplantable murine lymphoma that resembled clinical PTCL‐GATA3, we provide the first evidence for ATR inhibition as a candidate therapy for PTCL." (PMID 35510955, 2022). "To investigate whether expression of components of the ATR/CHK1 pathway itself were disrupted in RelA T505A cells, we performed qPCR analysis using RNA extracted from primary Eμ-Myc lymphomas." (PMID 36240065, 2022). "It was reported that DNA damage increases upon combining ATR suppression with MYC overexpression 23 and Chk1 inhibitors were highly effective in killing MYC-driven lymphomas 24, suggesting synthetic lethality as a treatment strategy for MYC-overexpressing tumors." (PMID 35844787, 2022). "In Myc-driven lymphoma, efficacy of epigenetic inhibitors of the bromodomain and extra-terminal domain (BET) family of bromodomain proteins can be enhanced by combination therapy with inhibitors of the DNA damage response kinase ATR." (PMID 28796244, 2017). "Overall, this suggests no major disruption of signalling by ATR and ATM in Eμ-Myc Rel−/− lymphomas but that specific targets exhibit changes in phosphorylation that could impact on the phenotype of these cells." (PMID 36240066, 2022).
microcephaly (25 papers, 2008 to 2025). A congenital or acquired developmental disorder in which the circumference of the head is smaller than normal for the person's age and sex. "Mouse models carrying hypomorphic mutations of the Atr gene imitate human ATR-SS including microcephaly and accelerated aging." (PMID 40105243, 2025). "Hypomorphic mutations of the ATR gene are responsible for human ATR-Seckel Syndrome (ATR-SS), a chromosome instability disorder characterized by dwarfism, severe microcephaly, growth retardation and intellectual disability." (PMID 34210973, 2021). "Mutations of the ATR gene have been reported in Seckel patients, who suffer from a rare genetic disease characterized by severe microcephaly and growth retardation." (PMID 30199583, 2018). "Seckel syndrome 1 (SCKL1) due to hypomorphic mutations in the ATR gene is characterized by microcephaly and mental retardation." (PMID 28620865, 2017). "Mutations in ATR have been identified in a subclass of SS patients, with microcephaly and severe growth delay being the pronounced phenotypes." (PMID 26908596, 2016). "Significantly, ATR deficiency in patients confers marked microcephaly, reflecting a role for ATR during neuronal embryogenesis, and additional abnormalities in growth and skeletogenesis." (PMID 26908596, 2016). "The conditional deletion of ATR in the CNS also causes microcephaly and defective cerebellar development." (PMID 23532176, 2013). "Loss of ATR is embryonic lethal and hypomorphic mutations mimicking those found in human Seckel syndrome result in severe microcephaly in mice and are synthetically lethal with ATM deficiency." (PMID 23532176, 2013). "This study reinforced the fact that haploinsufficiency of ATR has a functional impact in human cells but furthermore, that haploinsufficiency of ATR is associated with a human genomic disorder that exhibits microcephaly and short stature." (PMID 19440510, 2008). "Since the fibroblast cell line of patients (ATR-SS) demonstrates a defective DNA replication stress response, the mutations in ATR and other DNA damage response genes that cause microcephaly are regarded to impair the response to DNA replication stress in neural progenitor cells (NPCs)." (PMID 30846821, 2019). "This mutation is considered the cause of an impaired response to DNA replication stress, the main function of ATR, contributing to the pathogenesis of microcephaly." (PMID 30846821, 2019). "ATR-Seckle Syndrome which also presents with microcephaly and “bird-like” facial features occurs due to abnormal function in ATR, a protein that monitors single stranded DNA replication errors at replication forks." (PMID 27717373, 2016). "ATR–ATRIP patients are characterised by extremely severe microcephaly and growth delay, microtia (small ears), micrognathia (small and receding chin), and dental crowding." (PMID 23144622, 2012). "All four ATR/ATRIP patients displayed severe microcephaly and growth delay." (PMID 23144622, 2012). "Furthermore, haploinsufficiency of ATR, RPA1 and RFC2 is associated with several human genomic disorders that exhibit microcephaly and growth retardation." (PMID 19440510, 2008). "Therefore, WBS represents another genomic disorder that exhibits defective ATR-pathway activity wherein microcephaly and growth retardation are included in its clinical spectrum." (PMID 19440510, 2008). "The neurological symptoms, such as microcephaly, learning deficits and intellectual disabilities of ATR-SS patients and animal models, may well reflect abnormal neuron activities and thus suggest a potential role for ATR in postmitotic neurons." (PMID 34210973, 2021). "Although it is well known that ATM and ATR are required to maintain genomic integrity, the precise roles of ATM and ATR during brain development are not fully understood, especially related to neuropathology such as ataxia, neurodegeneration, and microcephaly observed in human patients." (PMID 28620865, 2017).
microcephaly (continued). "However, whereas ATR–ATRIP SS patients tend to have very marked microcephaly, growth delay, dental crowding, small ears and less severe skeletal abnormalities, the spectrum for MGS tends to be less marked microcephaly and growth delay but a striking impact on skeletal development." (PMID 23144622, 2012).